APOE (apolipoprotein E)
Diseases named in the same sentence as APOE in open-access papers (continued):
Sharing a sentence is not in itself a finding about the gene and the disease.
Hypercholesterolemia (continued). "They hypothesized that both intrauterine undernutrition, demonstrated by a lower birth weight, and the ApoE genotype participate in the development of hypercholesterolemia in childhood." (PMID 28480219, 2017). "In addition, genome-wide association studies have shown a strong association between Apolipoprotein E (APOE) p.Leu167del and the AD hypercholesterolaemia phenotype in a large family." (PMID 28868092, 2017). "Gender- and age-related differences in cardiovascular aging have been demonstrated in this genetically modified mouse, since hypercholesterolemia and male gender additively aggravate the entity of lipid deposition and vascular senescence in ApoE−/− mice of advanced age." (PMID 27618031, 2016). "Additionally, sildenafil treatment protected bone marrow cells of apoE−/− mice from the cytotoxic effect of hypercholesterolemia (0.42 ± 0.02)." (PMID 27229150, 2016). "Indeed, APOE-e4 carriers were overall higher in illness index scores and significantly more likely to have a history of hypercholesterolemia." (PMID 27486898, 2016). "Furthermore, in apoE-/- mice, which spontaneously develop hypercholesterolemia, there is evidence of decreased lymphatic drainage and spontaneous tissue swelling i.e. spontaneous murine LE." (PMID 27182733, 2016). "We focused our attention to examine the pathophysiological relevance of miR-24 induction by super-low-dose LPS, as miR-24 is among the most highly expressed miRNAs previously observed in both human patients with familial hypercholesterolemia, as well as in HFD-fed ApoE-deficient mice." (PMID 27824038, 2016). "Some studies have pointed to de acquisition of genes (ApoE alleles) allowing fat consumption without hypercholesterolemia." (PMID 26061730, 2015). "Clinical and experimental studies have shown endothelial dysfunction improvement after administration of BH4 in patients with hypercholesterolemia, and increased total biopterin and BH4 levels in aorta along with endothelial dysfunction improvement in apoE-deficient mice after antioxidant treatment." (PMID 26381906, 2015). "Therefore, apoE-knockout mice (apoE(−/−)) experience a severe, progressive form of hypercholesterolemia, making them the most commonly employed model for studying the adverse influence of cholesterol on various body." (PMID 26697490, 2015). "We therefore determined whether carbachol‐mediated endothelial Ca2+ signals differ in plaque‐prone aortic arch compared to plaque‐resistant thoracic aorta, of wild‐type and ApoE−/− mice, and how this is affected by age and the presence of hypercholesterolemia." (PMID 25344475, 2014). "To explore the effect in vivo we used ApoE−/− mice, a model of hypercholesterolaemia." (PMID 25161081, 2014). "Because ApoE OVX animals presented greater levels of plasma cholesterol than their respective controls, we sought to investigate if the observed increase in hypercholesterolemia contributed to the loss of renal function due to augmented lipid deposition in the kidney." (PMID 25422135, 2014). "Hypercholesterolemia found in the C. parvum-infected APOE knockout mice, even sustained following under nutrition, as shown in our study, may reflect impaired intestinal cholesterol delivery to the liver for metabolism." (PMID 24586873, 2014). "Hypercholesterolemia is one of the characteristics of ApoE-KO mice." (PMID 24708830, 2014). "Hypercholesterolemia did not cause any significant changes in the glomerular filtration rate of female ApoE mice (C57 Sham: 171 ± 17; ApoE Sham: 140 ± 26 μL/min)." (PMID 25422135, 2014). "In addition to alterations in the amplitude of the response to CCh in ApoE−/− mice, we also observed that hypercholesterolemia led to Ca2+ signals becoming more oscillatory in nature, particularly in aged mice and immediately adjacent to areas of plaque." (PMID 25344475, 2014).
Hypercholesterolemia (continued). "In the present study, we evaluated the influence of aging and hypercholesterolemia on oxidative stress, DNA damage and apoptosis in bone marrow cells from young and aged apoE−/− mice compared with age-matched wild-type C57BL/6 (C57) mice, using the comet assay and flow cytometry." (PMID 23385237, 2013). "Thus, the severe hypercholesterolemia in ApoE-/- mice attenuated the hypocholesterolemic phenotype seen in AdipoR2-/- mice." (PMID 24324556, 2013). "This higher inflammatory status of ApoE KO mice has been previously presented as a consequence of the absence of anti-inflammatory effects of apoE as well as the proinflammatory stimulus of hypercholesterolemia and oxidized lipoproteins." (PMID 23710353, 2013). "Furthermore, we have reported the protective effect of antioxidants, such as vitamins C and E, lutein, egg yolk, and a multivitamin-mineral complex on retinal oxidative stress and hypercholesterolemia-derived ultrastructural alterations in apoE−/− mice." (PMID 23738034, 2013). "Alternatively, the use of an atherogenic diet containing cholate could have induced far too severe of a hypercholesterolemia that may have overwhelmed the anti-atherogenic properties of macrophage-derived apoE." (PMID 22606237, 2012). "In the present study, we observed that the in situ short-term MNC therapy reverted cuff-induced occlusive thrombi in the carotid arteries from apoE-/- mice by the homing of EPCs, the reduction of ·O2− production and decreased apoptosis, even under conditions of hypercholesterolemia." (PMID 22849299, 2012). "In addition, results of this study provide evidence that apoE is produced by Kupffer cells in the setting of hypercholesterolemia." (PMID 22606237, 2012). "Indeed, aortic rings isolated from young (6-18-week-old) male and female apoE-/- mice fed a standard chow diet (hypercholesterolemia only) exhibit a preserved endothelial NO-dependent relaxation response to ACh when compared with wild-type control mice." (PMID 22082357, 2011). "However, the role of ApoE isoforms is complex with additional reports also implicating ApoE ε2 with hyperlipidaemia and ApoE ε4 with hypercholesterolaemia." (PMID 18823563, 2008). "In the absence of Dox the iKO mice had high cholesterol levels similar to that of the KO mice; in the presence of Dox, the iKO showed normal cholesterol levels, demonstrating that inducible expression of ApoE can lead to the reversion of the KO phenotype of hypercholesterolemia." (PMID 18464897, 2008). "Similarly, the protective effect of adiponectin against atherosclerotic lesion formation was observed in gAd-TG/ApoE-KO mice (ApoE-KO mice, which lack apolipoprotein E, develop atherosclerotic lesions accompanied by hypercholesterolemia), characterized by the overexpression of globular adiponectin." (PMID 40868889, 2025). "Studies with APOE2/3 isoforms have detected their protective effect for hypercholesterolemia, ischemic heart disease, and stroke, but APOE2/2 revealed an increased risk of vascular disease, thromboembolism, and arterial aneurysm, indicating that genetic variations in APOE do play a role in CVD risk." (PMID 39766777, 2024). "A rare pathogenic APOE variant c.636_645del/p.(Val213Trpfs∗35) showed complete segregation with LDL-C levels (122.8 ± 18.1 mg/dl), and normal triglycerides, which may be the cause of hypercholesterolemia in this family." (PMID 38122934, 2023). "Thus, it was possible that the hypercholesterolemia of the carrier of the p.Arg185 silent variant was not due to this APOE rare variant." (PMID 35628605, 2022).
Hypercholesterolemia (continued). "Among those, the most extensively investigated is the ApoE KO that lacks ApoE, a glycoprotein ligand for receptors that eliminates chylomicron remnants and very low-density lipoproteins (VLDLs), which exhibits spontaneous hypercholesterolemia and the formation of atherosclerotic lesions in vessels." (PMID 36359240, 2022). "Hypercholesterolemia in peripheral blood was observed in ApoE and Dscr-1 double null mice, whereas increased LDL levels could not be processed by larger aortic vessels due to atherosclerotic plaque formations, leading to worsening higher circulating LDL levels." (PMID 33895138, 2021). "However, there have not been more studies up to date involving Hypercholesterolemia, the APOE ε4 allele, and the Hispanic population." (PMID 34828374, 2021). "To study the effect of chronic hypercholesterolemia (i.e., higher-than-normal plasma cholesterol already apparent at 4-months of age) on systemic and neuro-inflammation and memory performance, we compared ApoE-/- mice to normocholesterolemic wild-type (WT) mice." (PMID 34349106, 2021). "ApoE-/- mice were first created in 1992, and may spontaneously develop hypercholesterolemia and AS." (PMID 32365054, 2020). "Furthermore, ApoE−/− mice are characterized by a significant increase of tau-phosphorylation and by enhanced AT8 signal (current study), contributing to the assumption that hypercholesterolemia causes tau hyperphosphorylation." (PMID 33029684, 2020). "Our results corroborate with transcriptome study which demonstrated that ApoE–/– associated with HF diet, promotes mRNA-level dysregulation of signaling pathways related with ECM synthesis, and repair in the tendon, suggesting mechanism of hypercholesterolemia-induced tendinopathy." (PMID 32656202, 2020). "Due to hypercholesterolemia, NO production was impaired in APoE KOs compared to the Sprague Dawley rats, and we hypothesized that it was even further damaged in diving ApoE KOs." (PMID 31695628, 2019). "In fact, the impact of APOE on brain IgG was once involved in Fernandez ‘s study, in which they reported increased brain levels of IgG and upregulation of activating Fc receptors in the brain of APOE knockout (APOE−/−) mouse, a well-established model of hypercholesterolaemia." (PMID 30700991, 2019). "It has been shown that miR-223 levels were enhanced in ApoE- and LDL-receptor deficient mice under high-fat diet and also, in patients with familiar hypercholesterolemia, and might be involved in regulating of liver gene expression due its role as intercellular communication system." (PMID 31850358, 2019). "However, we cannot attribute all the changes to binomial aging and hypercholesterolemia as apoE gene itself may participate in the clearance of apoptotic cells remnants and stimulate a pro-inflammatory response." (PMID 30185234, 2018). "In addition, previous reports revealed that hypercholesterolemia increased the expression of growth factors and that, in this regard, apoE acts to regulate the proliferation of hematopoietic stem/progenitor cells leading to a subsequent expansion of myeloid lineage." (PMID 30185234, 2018). "The treatment of diabetic apoE−/− mice with quercetin caused significant attenuation of plasma glucose (~25%) and abolished the hypertriglyceridemia (p < 0.05); however, this dose of quercetin did not reverse the hypercholesterolemia." (PMID 26388784, 2015). "Since hypercholesterolemia also triggers the release of angiotensin II, we asked whether captopril treatment prevented the down-regulation of neuron-specific genes in hypercholesterolemic ApoE−/− mice." (PMID 23801967, 2013).
Hypercholesterolemia (continued). "Therefore, the aim of this study was to examine the hypothesis that aging and hypercholesterolemia are associated with the enhanced production of ROS, DNA damage and apoptosis in bone marrow MNC from wild-type C57 and apoE−/− mice." (PMID 23385237, 2013). "Further, gene variants, including apolipoprotein E (APOE) isoforms, and single-nucleotide polymorphisms in genes encoding the LDL-receptor (LDL-R), apolipoprotein B (apoB), and proprotein convertase subtilisin/kexin type 9 (PCSK9) may result in severe hypercholesterolemia and hypertriglyceridemia." (PMID 39796476, 2024). "To determine the potential role of hypercholesterolemia in CRC, we first induced colorectal tumorigenesis with AOM/DSS in a well-established mouse model of hypercholesterolemia, the ApoE−/− mouse." (PMID 38755702, 2024). "This has mostly been demonstrated in different vessel segments from ApoE−/−, LDL receptor−/−, or apoE/LDL R−/− mice fed with a high-fat diet, thus featuring hypercholesterolemia." (PMID 35648220, 2022). "Differing from cholesterol-fed WT and apoE KO rabbits, WHHL rabbits had high levels of plasma LDLs, similar to human familiar hypercholesterolemia." (PMID 35712258, 2022). "This exaggerated ApoE−/−-mediated nonalcoholic fatty liver disease (NAFLD) and subsequent hypercholesterolemia." (PMID 33895138, 2021). "In an atherosclerotic ApoE−/− background or PCSK9 overexpression, Dscr-1 null mice revealed significant hypercholesterolemia leading to lipid accumulation in the peripheral tissues." (PMID 33895138, 2021). "Therefore, the effects of diet-induced hypercholesterolemia on cardiac function and remodeling were investigated up to eight weeks after myocardial ischemia-reperfusion (MI-R) injury which was induced in either normocholesterolemic (NC-MI) or hypercholesterolemic (HC-MI) APOE*3-Leiden mice." (PMID 31199833, 2019). "However, given the relatively low levels of hypercholesterolaemia that might be expected at age 43, it is unlikely to have influenced associations between cognition and APOE-ε4." (PMID 29317609, 2018). "Finally, the lack of ApoE caused severe hypercholesterolemia in mice." (PMID 29151984, 2017). "ApoE KO mice have impaired clearance of VLDL and chylomicrons from the blood, which results in hypercholesterolemia and favors the development of atherosclerotic lesions." (PMID 23710353, 2013). "We designed a four-week parallel controlled intervention on apolipoprotein E3 Leiden cholesteryl ester transfer protein (ApoE*3Leiden.CETP) transgenic mice with mild overweight and hypercholesterolemia." (PMID 21611179, 2011). "We found that the Paigen diet induced a more severe hypercholesterolemia and greater aortic atherosclerosis in PDZK1/apoE dKO mice than in the apoE KO controls." (PMID 19956623, 2009). "Our study, therefore, examined the direct contribution of LOX activity to arterial wall stiffening induced by chronic d-flow without confounding effects of hypercholesterolemia or ApoE inactivation." (PMID 39143955, 2024). "In summary, mechanical injury only led to disruption of endothelial integrity, whereas ApoE–/– mice only exhibited hypercholesterolemia rather than fatty and lipoproteins deposition in 8 weeks." (PMID 36818346, 2023).
Hypercholesterolemia (continued). "ApoE–/– mice treated with HFD for 8 weeks exhibited severe hypercholesterolemia, but no change in the aortic valve, as these mice usually take more than half a year to develop AVS." (PMID 36818346, 2023). "Our ApoE−/− rats only demonstrated a mild hypercholesterolemia phenotype, which did not translate to a visibly increased Achilles tendon lipid content." (PMID 37046262, 2023). "Mouse models of dyslipidemia lacking apolipoprotein E (apoE−/−) show reduced lymphatic integrity and transport function that worsens as hypercholesterolemia progresses, suggesting that the lymphatics themselves are dysfunctional." (PMID 37958806, 2023). "Consistently, our previous study also found that exposure to a potent mouse PXR ligand, pregnenolone 16α-carbonitrile (PCN), induced hypercholesterolemia in WT mice but did not affect plasma total cholesterol levels in hyperlipidemic ApoE−/− mice." (PMID 35406689, 2022). "The examination of the resulting impact of statin therapy for hypercholesterolemia revealed that cholesterol levels were actually reduced, particularly in the LDL fraction, which is an aftereffect of known processes involving ApoE apolipoproteins that transport cholesterol molecules." (PMID 36293327, 2022). "Although hypercholesterolemia was generally accompanied by higher-than-normal BP in aged ApoE-/- mice, cholesterol-lowering rather than BP-lowering therapy significantly improved the impaired spatial memory of aged ApoE-/- mice." (PMID 34349106, 2021). "Independent of additional miR155 knockout, our ApoE−/− mice fed a normal chow diet were characterized by substantial hypercholesterolemia and dyslipidemia." (PMID 34067440, 2021). "Further studies are needed to uncover why such plaques failed to grow with hypercholesterolemia in Dscr-1−/− and ApoE−/− mice." (PMID 33895138, 2021). "It is noteworthy that all four groups of bone marrow recipients displayed similar hypercholesterolemia, thus documenting that the differences in atheroprotection were not due to differences in plasma lipoprotein clearance in ApoE−/− mice." (PMID 34425108, 2021). "Here, we explored how lymphocyte trafficking and LN structure and function are affected by hypercholesterolemia that occurs in mice lacking apoE (apoE−/−)." (PMID 30972070, 2019). "They further indicate that this apoE function is mediated through the autocrine/paracrine modulation of cholesterol metabolism in DCs, and is independent of systemic hypercholesterolemia." (PMID 30082772, 2018). "Results from WT and apoE KO bone marrow chimera suggest that apoE from cells of hematopoietic origin has immunomodulatory functions, regardless of the onset of hypercholesterolemia." (PMID 30082772, 2018). "With regard to plasma lipid levels, our study showed that gugulipid administration caused hypercholesterolemia rather than reducing total and LDL cholesterol levels or changing LDL receptor expression in male wild-type, as well as ApoE KO, mice." (PMID 28910310, 2017). "We created a recombinant APOE form termed APOE4mut1 (apoE4 [L261A, W264A, F265A, L268A, V269A]) that in mice corrects hypercholesterolemia without triggering hypertriglyceridemia even at concentration as high as 170 mg/dL." (PMID 29770778, 2017). "However, adenoviral gene transfer of human apoE isoforms in apoE-deficient mice showed that overexpression of human apoE2 increased plasma triglycerides and cholesterol; by contrast overexpression of human apoE3 or apoE4 caused neither hypertriglyceridemia nor hypercholesterolemia." (PMID 28660014, 2017). "APOE-e4 carriers as compared to non-carriers were significantly more likely to have a history of hypercholesterolemia and were overall higher on their illness index scores." (PMID 27486898, 2016).